MIR95 (microRNA 95)
Synonyms: hsa-mir-95; MIRN95; miR-95
Gene: MicroRNA gene on chromosome 4 (8,005,301 to 8,005,381, reverse strand). Ensembl gene ENSG00000207807.
Gene Ontology:
Biological process: cellular response to amino acid stimulus; long-term synaptic potentiation; response to bacterium
Homologues: Orthologues: chimpanzee ptr-mir-95 (100% identical), macaque mml-mir-95 (100% identical).
Diseases named in the same sentence as MIR95 in open-access papers:
MIR95 is named in the same sentence as 3 diseases in open-access papers, as found by Europe PMC text mining. Sharing a sentence is not in itself a finding about the gene and the disease. The quoted sentences say what the papers report.
breast carcinoma (1 paper, 2016). "For example, while MIR95 is highly expressed in both prostate and lung cancers and have oncogenic function; the anti-proliferative role of MIR95 was observed in breast cancer MCF-7 cells." (PMID 27462775, 2016).
MIR95 also shares sentences with these, for which no sentence is quoted: lung carcinoma (1 paper); pancreatic adenocarcinoma (1).